PON1 (paraoxonase 1)
Diseases named in the same sentence as PON1 in open-access papers (continued):
Sharing a sentence is not in itself a finding about the gene and the disease.
cancer (continued). "Despite different cell lineages, different oncogenic drivers, and different drugs, we found a widespread elevation of fucosylated secretome PON1 levels in multiple cancer cells upon targeted therapy." (PMID 36961502, 2023). "Our discovery of PON1 fucosylation as a component of the pan-cancer TIS contextualizes its systemic regulation in cancer patients upon therapy." (PMID 36961502, 2023). "A number of recent studies investigating the relationship between PON1 and cancers showed low expression and activity of this enzyme." (PMID 36833509, 2023). "Low PON1 activity affects its intrinsic functions and increases oxidative stress, suggesting a worse prognosis in patients with cancer." (PMID 35453382, 2022). "PON1 is expressed at low levels in the blood of patients with a variety of cancers, and levels are further decreased after treatment." (PMID 35847896, 2022). "Nevertheless, information about the PON1 gene and DNA methylation in cancer development is still scarce." (PMID 35453382, 2022). "The different results obtained by various researchers suggest the need for further studies to establish the actual role of PON1 in different types of cancer." (PMID 36290747, 2022). "Previous studies have observed circulatory alterations in PON1-related variables in patients with different types of cancer." (PMID 36552602, 2022). "PON1 is a calcium-dependent hydrolase protein mainly involved in the occurrence and development of cancers through the regulation of oxidative stress and inflammation." (PMID 35847896, 2022). "When comparing concentrations across grading subgroups, PON1 levels were found to be statistically significantly higher in G1 cancers in premenopausal patients (p = 0.043)." (PMID 36290747, 2022). "It is also suspected that cancer cells can scavenge serum PON1 and take advantage of its antioxidative effects." (PMID 35204228, 2022). "Post-RT, higher values of neutrophils, total leukocytes, PON1 activity and VLDL-cholesterol, and lower eosinophils, were associated with a higher probability of cancer death." (PMID 36552602, 2022). "Alterations of PON1 activity have been widely demonstrated in several human chronic diseases and in cancer." (PMID 34696795, 2021). "Currently, serum PON1 activity appears to be decreased in many types of cancers, and this topic has been the subject of a recent meta-analysis." (PMID 34356595, 2021). "Our research group observed decreased PON1 activities in patients with cancers of the breast, lung, head and neck, and rectum who, fully or partially, recovered post-radiotherapy." (PMID 34356595, 2021). "PON1, a high-density lipoprotein- (HDL-) associated protein, is known to contribute to cancer development." (PMID 32076459, 2020). "Among these we identify induction of plasma SAAs and reduction of plasma PON1 as potential new atrokines in cancer cachexia." (PMID 33063952, 2020). "CEA, CA12-5 and CA19-9 are the most commonly used clinical index to screen cancer, so we also assessed the diagnostic value of CEA, CA12-5, CA19-9 in combination with PON1 in CRC." (PMID 33046970, 2020). "Our data suggest SAA and PON1 as potential novel atrokines for cancer cachexia and indicate localized inflammation in atrophying muscles independent of the plasma proteome." (PMID 33063952, 2020). "Paraoxonase 1 (PON1), a multifactorial antioxidant enzyme, has a defensive role against oxidative stress, which is believed to contribute to cancer development." (PMID 31983193, 2020). "Although it is suspected that antioxidative function of PON1 contribute to cancer development, it currently lacks detailed mechanism to prove such." (PMID 28467805, 2017). "Recently, serum PON1 activity has been reported to be decreased in several types of cancer including BC." (PMID 29176871, 2017). "Collectively, addressing PON1 needs to be completed so we understand better the roles of PONs in redox system and cell death regulation in cancers." (PMID 28467805, 2017).
cancer (continued). "From this, it is worth examining if cancer cells have ways to scavenge serum PON1 and take advantage of its known metabolic functions such as antioxidative and anti-inflammatory effects." (PMID 28467805, 2017). "Despite these initial findings, the interaction of serum PON1 levels with cancer is not completely known." (PMID 17362500, 2007). "PON1 polymorphism association studies in cancer differ among populations; there are no studies on the Mexican population." (PMID 40149317, 2025). "Activity of PON1 is also reduced in various types of cancer." (PMID 38125616, 2024). "Furthermore, SR-B1 was shown to be upregulated in cancer cells, and PON1 activity was reduced in patients with cancer." (PMID 36671490, 2023). "The decreased activities of PON1 in cancer might also be connected with the modification in protein glycosylation, affecting PON1, which is a glycoprotein." (PMID 36833509, 2023). "There are studies reporting a decrease in PON-1 activity in cancer patients." (PMID 36969000, 2023). "Collectively, these consistently support our hypothesis that PON1 core fucosylation is a critical and functional component of the cancer TIS that promotes targeted therapy resistance." (PMID 36961502, 2023). "Identification of fucosylated PON1 as a critical component of therapy-induced cancer secretomes." (PMID 36961502, 2023). "There is a consistent correlation between cancer and decreased serum PON1 activity." (PMID 36969000, 2023). "Based on studies related to the presence of cancer and the epigenetic regulation of PON1, the corresponding data remain scarce in the literature; however, the PON2 and PON3 genes have been studied, focusing on the levels of the methylation profile of these genes." (PMID 35453382, 2022). "As previous studies have shown, it is obvious that PON1 plays a role in cancers." (PMID 36290747, 2022). "The possible correlation of serum PON1 activity with the risk of cancer recurrence after RT is not yet fully explored, with few such studies described in the literature and none about PCa." (PMID 35204228, 2022). "Undoubtedly, the gene expression of PON1 will remain challenging to study and therefore, more studies at different levels of scientific research are required for the complete elucidation of the role of this enzyme and its specific relationship with cancer." (PMID 35453382, 2022). "Therefore, targeting PON1, redox-sensitive pathways and transcription factors promise disease prevention, including cancer." (PMID 35453382, 2022). "Based on the studies, it is evident that PON1 plays a vital role in cancer." (PMID 35453382, 2022). "This review focuses on the relationship between PON1 and cancer." (PMID 35453382, 2022). "Several studies have also reported decreased serum PON1 activity in cancer patients." (PMID 35204228, 2022). "Of note, PON1 serum activity is reduced in cancer patients of various entities." (PMID 35577388, 2022). "The correlation of PON1 with the risk of cancer recurrence after radiotherapy (RT) is not yet explored." (PMID 35204228, 2022). "Epigenetic modifications focused on PON1 studies and cancer development." (PMID 35453382, 2022). "This may lead to a hypothesis that the mechanisms involved in hypoxia-induced radioresistance also lead to a decrease in cancer-related increased oxidative stress and thus partially prevent the decrease of serum PON1 activity." (PMID 35204228, 2022). "Therefore, targeting PON1, redox-sensitive pathways, and transcription factors promise prevention and therapy in the development of several diseases, including cancer." (PMID 35453382, 2022). "Recently, many studies have focused on the relationship between PON1 and cancer." (PMID 35453382, 2022). "A recent meta-analysis showed decreased serum PON1 activity in patients with cancer, suggesting an impaired ability to combat oxidative stress, with potential implications in cell proliferation, promotion of genetic instability, and alterations in cellular sensitivity to chemotherapy." (PMID 33886674, 2021).
cancer (continued). "Lower serum PON1 activity has been reported in cancer patients." (PMID 31052559, 2019). "In summary, in allele contrast model, we have found that there were not association between PON1-Q192R allele and reduced overall cancer risk." (PMID 31467900, 2019). "In the last years, there is a growing interest on the role of PON1 in cancer." (PMID 31430977, 2019). "Moreover, in individuals who have been treated for cancer, oxidative stress markers decreased, and the activities of the enzymes antioxants, superoxide dismutase, catalase, paraoxonase-1 higher." (PMID 31052559, 2019). "Additionally, it was reported that HDL can reduce the PON-1(paraoxonase) free-radical-scavenging ability by inhibiting the association of PON-1, thus providing some protection for the severity of cancer." (PMID 30249816, 2018). "It was found that expression or activity of PON1 was lower in cancer patients than controls." (PMID 29254148, 2017). "This also collectively suggests that LC might potentially exploit the antioxidative function of PON1 to benefit cancer cell growth and survival." (PMID 28467805, 2017). "Several studies reported that expression or activity of PON1 decreased in several cancers." (PMID 29254148, 2017). "Factors have been described that are able to modulate PON1 gene expression such as some interleukins and tumor necrosis factor-α, explaining the anti-inflammatory effects induced by the enzyme in some disease contexts including cancer." (PMID 28467805, 2017). "There are relatively few studies on in PON1 activity in cancer." (PMID 17362500, 2007). "In addition, there are reports that PON1 enzyme activity is lower in cancer patients compared to healthy controls in various cancer types (lung, breast, gastrointestinal, etc.), which might reflect a reduced antioxidant defense." (PMID 41303537, 2025). "Recently, PON1 AREase and POase activity has been assayed in a cohort of women with breast cancer treated with doxorubicin (DOX) to determine whether there is any association with cancer therapy-related cardiac dysfunction development (CTRCD)." (PMID 36833509, 2023). "In addition, PON1 is a glycoprotein, alterations of the protein glycosylation patterns could occur as previously observed in proteins during cancer progression." (PMID 34696795, 2021). "PON1 levels may act as an indicator of oxidative stress in cancer." (PMID 34439311, 2021). "Therefore, further studies should assess whether PON1 may be a viable target to protect against cancer cachexia." (PMID 33063952, 2020). "Our findings suggest SAAs and/or PON1 may provide novel mechanisms of cancer cachexia." (PMID 33063952, 2020). "Because paraoxonase 1 (PON1), which is located on chromosome 7q21.3, not only decreases oxidative stress but is also implicated in the development of many cancers, investigators have assumed that PON1 polymorphisms might be associated with an increased risk of BC." (PMID 28445984, 2017). "However, explicit reporting of the cancer-causing mechanism of PON1 in these cancers has not yet been elucidated despite these associations." (PMID 28467805, 2017). "Although several studies have attempted to investigate association between PON1 polymorphisms and cancer susceptibility, to the best of our knowledge, no study has focused on the relationship between PON1 polymorphisms and chemotherapeutic outcomes including the response rate, PFS, and OS." (PMID 25545243, 2014). "However, even if such bias existed and PON1 genotype influenced cancer prognosis, it is unlikely this could account fully for the moderately strong association we observed between CBT and PON1C-108T." (PMID 16002382, 2005). "The PON family of enzymes, comprising PON1, PON2, and PON3, are highly expressed in various cancer cells and play critical roles in promoting cell survival and metastasis." (PMID 40794328, 2025).
cancer (continued). "Among the downregulated proteins, paraoxonase 1 (PON1), which protects against oxidative stress, and C4BPA, which inhibits cancer progression by promoting antitumor T cells, are notable." (PMID 41271007, 2025). "Surviving cancer cells that managed to escape the cytotoxic effects of GEM or 5‐FU were investigated for the expression of four CSC markers: ALDH1A1, PON1, CD44, and EpCAM." (PMID 36400567, 2023). "Among the 7 model genes, 4 genes were differentially expressed in HCC cells and normal para-cancer tissues, namely, ANP32B, FTCD, ADH4 and PON1." (PMID 35413690, 2022). "We have shown that circulating levels of the enzyme paraoxonase-1 (PON1) are decreased in patients with BC, and other types of cancer, compared to the healthy population." (PMID 36552602, 2022). "The GBM model with an AUC of 0.750, indicated that post-RT neutrophils, leukocytes, eosinophils, PON1 activity, and VLDL-cholesterol were the most efficient parameters in the discrimination between stabilization of disease and cancer death." (PMID 36552602, 2022). "PON1 and PON3 are involved in the lipoxygenase pathway, leading to the generation of eicosanoids impacting cancer development, progression and immune responses." (PMID 34439311, 2021). "However, PON1 is not the only component of the HDL particles to have been associated with cancer." (PMID 31295833, 2019). "In the following section, we give an overview of studies that assessed expression of PON1, PON2, or PON3 in various cancers, with the majority of studies seemingly reporting a deregulation of these proteins." (PMID 22666600, 2012). "For instance, some of the molecules reported in the review (e.g., PON1) were evaluated in small groups of patients, but they have still not been tested for their ability to detect cancer in vast cohorts." (PMID 41008635, 2025). "Interestingly, the expression of ALDH1A1 and PON1 was significantly higher in NAT than in TN (P < 0.01), suggesting a higher proportion of cancer cells with stem cell properties in the residual tumors following NAT compared with TN tumors." (PMID 36400567, 2023). "This suggests that the determination of standardized PON1, PON3, and MDA levels may be a useful biomarker in predicting recurrence following cancer surgery." (PMID 32549522, 2020). "Although the relative studies about PON1 and DNA methylation are not so much and it has been a forward‐looking subject due to the non‐negligible role of PON1 played in the development of cancers including RCC." (PMID 31400051, 2019). "Therefore, it was not surprising that the paraoxonase 1 activity was lower in cancer patients who had, as shown, greatly increased markers of OS." (PMID 37965473, 2023). "We may, however, suggest two possible mechanisms based on the role of PON1 and the metabolic changes induced by the cancer-related increased oxidative stress, which are not mutually exclusive." (PMID 35204228, 2022). "Since elevated oxidative stress is inherent to cancer development, a lack of PON1 activity could be expected in this condition." (PMID 33805921, 2021). "According to our pathway detection results, PON1 downregulation may not directly affect the invasiveness and metastasis of tumor cells as PON1 is located downstream of cancer-related biological processes." (PMID 30477582, 2018). "Interestingly, this uptake persisted upon H2O2-induced oxidative stress in A549 cells but not in L132 cells supporting that PON1 uptake can be an adaptive response mechanism of cancer cells to oxidative stress." (PMID 28467805, 2017). "PON1 inhibits LDL peroxidation and decomposes LDL peroxidation products into non-toxic small molecules in which way related to cancer occurrence 11,12." (PMID 33046970, 2020). "The negative correlations of ADH4, PON1, and PZP expression with the IC50s of the anti-cancer drugs indicated that the LSGs might affect the efficiency of these drugs in HCC." (PMID 38374122, 2024).
tumor (49 papers, 2005 to 2026). "PON1 is also implicated in the apoptosis that ER stress causes in tumor cells and serum PON1 level is a powerful prognostic factor and can be used to evaluate microvascular invasion in HCC." (PMID 36003068, 2022). "Future studies with larger sample sizes and in women of different ethnicities are needed to confirm the utility of PON1 polymorphisms as genetic markers for the risk of developing BC and for tumor prognosis." (PMID 28445984, 2017). "Meanwhile, PON-1 levels decrease in response to oxidative stress, which could be associated with tumor progression." (PMID 40559770, 2025). "This distinction may explain the stronger association of PON-1 with tumor grading and highlights its potential as a more robust and clinically relevant marker." (PMID 39765802, 2024). "According to the important role of PON1 in the development of tumor and the correlation between genotype and phenotype, we speculate that the variation of PON1 gene Q192 R and L55M may be related to tumor susceptibility." (PMID 31467900, 2019). "We found that PON1-55M variant was associated with an increased risk of BC in these patients and may play an important role in tumor progression." (PMID 28445984, 2017). "However, a decrease in PON1 might still cause changes in tumor cells, especially tumor-derived inflammation, autophagy, and apoptosis." (PMID 30477582, 2018). "Our study raises a stirring possibility on the significance of identifying critical effectors in supporting speculations such as that LC cells uptake PON1 from the blood through its HDL-associated mechanism to benefit tumor growth and metabolism via its antioxidative function." (PMID 28467805, 2017). "The results of TCGA-LIHC dataset analysis showed that compared with normal tissues, CDC20, LPCAT1, and SPP1 were significantly up-regulated and PON1 was significantly down-regulated in tumor tissues." (PMID 40404896, 2025). "The RT-qPCR analysis revealed significantly decreased expression of ESR1, APOA1, IGF1, PPARGC1A, SERPINE1 and PON1 in tumor tissues compared with adjacent normal tissues (P < 0.05)." (PMID 40317014, 2025). "In GSE25097 dataset, compared with normal tissues, the expressions of CDC20, LPCAT1, and SPP1 were significantly upregulated, while PON1 was significantly downregulated in tumor tissues, which was consistent with the results in TCGA." (PMID 40404896, 2025). "Increased CDC20, LPCAT1, and SPP1 and reduced PON1 were found in tumor tissues than normal tissues, as well as in advanced patients than early-stage patients." (PMID 40404896, 2025). "Patients with low PON1 expression manifested significant differences in pathology severity and tumor size and grade." (PMID 39594433, 2024). "The other tissues also presented expressional heterogeneities of the genes (normal livers: ADH4 and PON1; metastatic lymph nodes and portal vein tumor thrombus: PON1 and NR0B1) in their hepatocyte subclusters." (PMID 38374122, 2024). "Global and PON1-specific secretome de-N-glycosylation both limited the expansion of resistant clones in a tumor regression model." (PMID 36961502, 2023). "HDL-C, a potential tumor inhibitor, plays anti-inflammatory and antioxidant roles mainly through apolipoprotein A1(ApoA1) and paraoxonase 1(PON1)." (PMID 36811728, 2023). "PON1 is involved in inhibiting the adhesion of leukocytes, reducing the chronic inflammation, and suppressing the tumor invasion or metastasis." (PMID 36632140, 2023). "GSH is a vital antioxidant that is capable of inhibiting the tumor formation process, while PON-1 has its antioxidative and anti-inflammatory activities." (PMID 36308603, 2022). "A previous study found that decreased serum PON1 was significantly correlated with tumour load, consistent with our findings that PON1 levels were negatively correlated with clinical stage and T classification." (PMID 35847896, 2022).